IRF9 (interferon regulatory factor 9)
Diseases named in the same sentence as IRF9 in open-access papers (continued):
Sharing a sentence is not in itself a finding about the gene and the disease.
infection (continued). "Similar to WT STm infection, genes involved in the regulation of immune responses (ATF3, BATF3, ETS2, IRF9, NFκB2, MAFA, TNFAIP3), effector functions, (CCL4, CD200L, CD40, CD72, CD80, IL18) and TLR signaling, (EAF2, TLR15, TRAF3IP2, TOLLIP) were upregulated after ΔprgH STm infection in both models." (PMID 37854334, 2023). "Notably, IRF9 expression was not affected by infection with either virulent or attenuated ASFV strains, supporting the idea that the virus specifically induces STAT1 and STAT2 degradation to counteract IFN-I signaling." (PMID 34512601, 2021). "Indeed, a knockout of IRF9 completely abolished the expression of ISGs upon infection with C. acnes whereas it did not affect the proinflammatory cytokine response." (PMID 33178195, 2020). "Noticeably, STAT1/STAT2 and IRF9 form a transcriptional complex upon activation of type 1 IFN receptors; this complex can subsequently translocate to the nucleus and induce the expression of a broad spectrum of IFN-stimulated genes that serve to contain infection." (PMID 29084769, 2017). "Interestingly, while IRF9, STAT1, and STAT2 were found in the nucleus of IFN-I treated PAM cells after 8 hpi, their localization was primarily cytoplasmic after 16 hpi, suggesting that both attenuated and virulent strains impair the nuclear translocation at late times of the infection." (PMID 34512601, 2021). "In line with IFNRT, also KO of IRF9 again prevented the upregulation of IRF7 and also IRF2, but peculiarly, different from in the infection setting it did not lead to augmentation of IRF1 induction." (PMID 34685580, 2021). "Some of these molecules (IRF7, IRF9, STAT1, STAT2) are known ISGs and were upregulated in wild-type but not in IFNAR1−/−IL-28Rα−/− epithelia at 24 hours post infection." (PMID 24278020, 2013). "Therefore, we measured the levels of intracellular GABA, the intermediate product of glutaminolysis, and found that Ifnar1-/- but not Irf9-/- had higher levels of GABA before and after infection." (PMID 34237114, 2021). "STAT1 mRNA levels were increased in both HRV16 and HRV1B infection than mock (p = 0.036 and p = 0.014, respectively) whereas STAT2 mRNA levels were increased in HRV1B infection, not in HRV16, than mock (p = 0.040), whereas IRF9 mRNA levels were not increased in HRV16 and HRV1B infection." (PMID 34838080, 2021).
tumor (59 papers, 2010 to 2026). "IRF9, an interferon response marker, is primarily known for its role in anti-viral immunity and has been linked to tumor growth and metastasis." (PMID 40858590, 2025). "The differential levels of PTBP2 and IRF9 induced chemotaxis of tumour-associated monocytes and macrophages through chemokines and thereby limited NB growth." (PMID 37887559, 2023). "Loss of STAG2 results in IRF9 activation, which in turn upregulates PD-L1 expression in cancer cells, suggesting a tumor suppressor function in immune evasion." (PMID 35388001, 2022). "Similarly, IRF9, whose overexpression has been reported to cause resistance of tumor cells to drugs and radiation and exert oncogenic effects, has also been shown to be a key regulator for mediating the antiproliferative effect of IFN-α in tumor cells elsewhere." (PMID 39900908, 2025). "Additionally, deficiency of IRF9 reduced tumor burden in a spontaneous mouse model of CRC." (PMID 35205671, 2022). "Moreover, IRF9 overexpression is associated with the inflammation recognized as the PsP of tumor." (PMID 27421136, 2016). "PTMRS was enriched in immunosuppressive T-cell subsets, and IRF9 was identified as a tumor-promoting factor." (PMID 41403935, 2025). "Spatial distribution maps further confirmed that PTMRS signatures and IRF9 expression were markedly elevated in tumor tissues." (PMID 41403935, 2025). "Immunohistochemistry revealed markedly higher IRF9 levels in tumor than in normal tissues, a finding corroborated by paired analyses of ccRCC specimens." (PMID 41403935, 2025). "Overall, the inhibition of FAT1 promoted tumor growth in vivo, whereas the overexpression of STAT1/IRF9 inhibited the tumor-promoting effect induced by FAT1 knockdown." (PMID 39781458, 2025). "Like this, in the SETUP (Sequential Evaluation of Tumors Undergoing Preoperative Chemotherapy) trial, TNBC patients with low tumor IRF9 expression during chemotherapy had a seven-fold higher rate of metastatic recurrence." (PMID 39062738, 2024). "Overexpression of IRF9 or STAT2 slowed BRAFis-induced tumor shrinkage, while knockdown of IRF9 or STAT2 accelerated BRAFis-induced tumor shrinkage." (PMID 39802949, 2024). "IRF9 is involved in immunomodulation, cell cycle regulation, cell survival, and cell differentiation, impairing immune surveillance, which allows tumor cells to evade immune detection." (PMID 39791702, 2024). "Consistent with activation of the type I IFN pathway, we found that MUC1 significantly associates with (i) STAT2 and IRF9 expression in TNBC tumors and (ii) IRF9 in a scRNA-seq dataset from TNBC tumor cells." (PMID 35681561, 2022). "The colons of Irf9−/− mice had a reduced tumor burden in terms of both number of tumors and size compared with WT mice." (PMID 35205671, 2022). "IRF9 is primarily known to play an essential role in anti-viral immunity, but is also involved in central processes of tumor cells, like growth regulation." (PMID 36077645, 2022). "We first detected the mRNA level of IRFs in PC, revealing that the level of IRF2, IRF6, IRF7, IRF8 and IRF9 were elevated in tumor tissues in PC." (PMID 35012444, 2022). "We found that the level of IRF2, IRF6, IRF7, IRF8 and IRF9 were upregulated in tumor tissues in PC (P < 0.05)." (PMID 35012444, 2022). "We found that ApcMin/+Irf9−/− mice had a reduced tumor burden compared with ApcMin/+ control mice in terms of both the number and size of tumors." (PMID 35205671, 2022). "ATF7IP knockout induces interferon signaling through IRF7 and IRF9 upregulation, enhancing tumor immunogenicity and anti-tumor immunity via increased T cell activity." (PMID 36497341, 2022). "We then monitored body weight changes and tumor prevalence in WT and Irf9−/− littermate mice 80 days after AOM injection." (PMID 35205671, 2022). "Specifically, IRF3, IRF7, and IRF9 were significantly upregulated in tumor tissues, whereas IRF4 was downregulated (P < 0.001)." (PMID 34488791, 2021).
tumor (continued). "In accordance with tumor staining results, we observed increased levels of IRF9 and VCAN in IRF9-overexpressing tumors; PCNA staining also showed an increase in PCNA expression in these tumors." (PMID 33430083, 2021). "We also confirmed the tumor-promoting and tumor-inhibiting properties (i.e., proliferation and migration) of IRF9 via its overexpression or silencing, respectively, in A427 cells." (PMID 33430083, 2021). "In an investigation of tumor behavior, IRF9 overexpression led to increased proliferation and migration, whereas IRF9 knockdown resulted in reduced proliferation and migration." (PMID 33430083, 2021). "VSMCs are activated by IRF9 to facilitate vessel repair and neovascularization, thereby supporting tumor development with angiogenesis." (PMID 33430083, 2021). "To confirm the stable overexpression of IRF9 and the associated target gene VCAN, we isolated RNA from tumor homogenate." (PMID 33430083, 2021). "In accordance with in vitro results, IRF9-overexpressing cells showed increased tumor growth and tumor weight." (PMID 33430083, 2021). "Growth factor-related genes are also associated with tumor metastasis, among which LTα, TNFRSF12α, TNFRSF25, TNFRSF4, and IRF9 can mediate HNSCC tumorigenesis and metastasis through the NF-κB signaling pathway." (PMID 33330624, 2020). "Interferon regulatory factor 1 and 9 (IRF1 and IRF9) are transcriptional regulators of interferon-B and tumor suppressors of IFN-inducible genes." (PMID 32101552, 2020). "In summary, we point out the role of IFNβ activated Stat1/Stat2/IRF9 signalling in cancer invasion plasticity, aside from its known role as a tumour suppressor." (PMID 32872349, 2020). "Immunohistochemical staining revealed heterogeneous expression of IRF9 across the SETUP trial cohort, with some tumors expressing high tumor IRF9 whilst others had low or undetectable levels." (PMID 31482136, 2019). "Here, we demonstrate that tumor-inherent IRF9 is an important biomarker that reflects both active IFN signaling and a subsequent TRM signature, indicative of a tumor-targeted T-cell memory response." (PMID 31482136, 2019). "All patients included in the trial had surgery post-chemotherapy and hence we also assessed IRF9 expression in the non-tumor epithelial tissue of complete responders." (PMID 31482136, 2019). "Our findings indicate IRF9 as a robust biomarker that can reflect overall tumor heat and metastasis-free survival in TNBC." (PMID 31482136, 2019). "The expression of IRF9 mid-chemotherapy was associated with risk of distant relapse, whereby patients with low tumor IRF9 expression mid-chemotherapy were over seven times more likely to develop metastatic relapse than patients with high tumor IRF9 expression." (PMID 31482136, 2019). "We highlight the association of tumor resident T cells along with tumor cell intrinsic type I IFN signals with a favorable prognosis in TNBC, and identify interferon regulatory factor 9 (IRF9) as a candidate prognostic biomarker in this subtype." (PMID 31482136, 2019). "As with the SETUP trial, staining was homogeneous in individual tumors and heterogeneous across patients, with some tumors expressing high tumor IRF9, while others had low or undetectable levels." (PMID 31482136, 2019). "In order to learn the reason for enhanced tumor growth after IRF9 knockdown, we performed hematoxylin and eosin(H&E) and immunohistochemistry (IHC) staining on five pairs of 786-O SCR and IRF9-69 tumors." (PMID 30355451, 2018). "In many cases the protein expression levels of PBRM1, SETD2 or BAP1 correlated with that of STAT2 or IRF9 on the same tumor samples." (PMID 30355451, 2018). "To confirm IFNα/β did not play a role in this resistance, we ablated the ability of tumours to respond to IFNα/β via IRF9 knockdown, and generated identical results." (PMID 23762429, 2013). "IP of IRF9 in THP1-MΦ coprecipitated the FLAG-tagged STAT2 derived from tumor cells." (PMID 41321309, 2025).
tumor (continued). "Interferon Regulatory Factor 9 (IRF9) is upregulated in pulmonary artery smooth muscle cells in PAH and is related to mitochondrial dysfunction; in LC, it is associated with reduced survival, promoting proliferation, migration, and tumor growth." (PMID 41440381, 2025). "This study also suggested that IRF9 is a marker for a T-cell-inflamed tumor." (PMID 39062738, 2024). "It found that tumor-associated macrophages had upregulated genes regulated by IRF2, IRF7, IRF9, and STAT2, and downregulated genes regulated by Fos/Jun and IRF8, revealing decreased inflammatory response, TNF-α-induced proliferation, and reactive oxygen species production pathways." (PMID 39034998, 2024). "Therefore, we suggested that the level of IRF3, IRF6, IRF7, IRF8 and IRF9 were upregulated in tumor tissues of PC." (PMID 35012444, 2022). "Transcription factor (TF) activity prediction, using the DoRothEA resource, to identify potential regulons responsible for the signalling and phenotypes associated with HPS in HiFi tumours revealed a strong association with STAT1, STAT2, IFN (IRF1, IRF9) and NFκB (NFKB1, REL, RELA, RELB) TFs." (PMID 35477539, 2022). "The effects of U-ISGF3 on DNA damage resistance and the fact that IRF9 overexpression leads to resistance against several chemotherapeutics indicates that IRF9 could affect tumor therapy, which in turn helps explain the oncogenic properties of IRF9." (PMID 33430083, 2021). "In addition, injection of shIRF9 cells showed reduced tumor growth and tumor weight in the IRF9-knockdown group." (PMID 33430083, 2021). "Furthermore, we found that the mRNA expression of IRF9 was increased in human non-tumor and lung tumor patient samples." (PMID 33430083, 2021). "In addition, siRNA experiments showed that VCAN diminished the tumor promoting effects of IRF9 and indicated the involvement of the tumor suppressor CDKN1A." (PMID 33430083, 2021). "The same trend was seen post-chemotherapy where lack of tumor IRF9 in partial or non-responders was associated with accelerated distant relapse." (PMID 31482136, 2019). "To assess whether the tumor inherent expression of IRF9 reflected active IFN signaling pathways we performed whole-genome expression analysis on the same tissues derived from the SETUP trial." (PMID 31482136, 2019). "Together, these data suggest that IRF9 is a surrogate marker for a T-cell inflamed tumor." (PMID 31482136, 2019). "Furthermore, we identified the tumor inherent interferon regulatory factor IRF9 as a marker of active intratumoral type I and II interferon (IFN) signaling and reduced risk of distant relapse." (PMID 31482136, 2019). "Suppression of IRF9 in 786-O or Ren-02 cells greatly enhanced tumor growth." (PMID 30355451, 2018). "IRF9 plays a vital role in suppressing tumor in multiple ways." (PMID 27421136, 2016). "Additionally, the biological mechanisms of IRF9 and XRCC1 underlying tumor suppression, prevention, and inflammation were carefully addressed." (PMID 27421136, 2016). "Importantly, we found that the knockdown persisted in vivo through immunohistochemistry for IRF9, and that the knockdown had similar tumour growth kinetics to the K1492 scrambled control." (PMID 23762429, 2013). "These include identifying the role of Interferon Regulatory Factor 9 (IRF9) as a key factor in eliciting the antiproliferative effects of IFN-α as well as identifying genes induced by IFN that are involved in recognition of tumor cells." (PMID 20664817, 2010). "Furthermore, IRF9 could represent a therapeutic target, as its modulation may enhance anti-tumor immunity and improve the efficacy of checkpoint blockade." (PMID 41403935, 2025). "The key role of IRF9 in modulating immune responses may influence the efficacy of immune checkpoint therapies, as the impact on interferon-stimulated gene expression might affect tumor resistance to immune-based treatments." (PMID 39791702, 2024).
tumor (continued). "Therefore, we investigated whether the reduced tumor development in the colons of Irf9−/− mice could be due to reduced colonic inflammation." (PMID 35205671, 2022). "However, the role of IRF9 in tumor development and progression remains unclear with the available literature being contradictory." (PMID 33430083, 2021). "IRF1, IRF9 and STAT1 in lymphoid cells of C1 participated in anti-tumor immune response by impacting target genes CD8A, HLA-A/E, TAP1 and PD-1." (PMID 42074110, 2026). "In vivo, we observed the upregulation of IRF9, p‐PI3K, p‐AKT, and CD163 in subcutaneous tumor tissues from nude mice injected with ITGβ8‐overexpressing A549 cells." (PMID 39535362, 2025). "H&E and IHC revealed that the protein levels of IRF9 and CD163 were greater in the tumor tissues from the ITGβ8‐overexpressing group than in those from the control group." (PMID 39535362, 2025). "In contrast, the proteins CAMK2A, IL33, IRF9, and TRAF5 were primarily expressed in normal tissues and exhibited reduced expression in tumor tissues." (PMID 40893939, 2025). "We then assessed the expressions of GLDC and ISGF3 in xenografted tumor tissues and confirmed decreased GLDC and increased IRF9 and STAT2 expressions." (PMID 39781465, 2025). "Although a different tumor type, the current research also found a positive correlation between PDL1 and IRF9 in HNSC; however, such finding needs to be verified by future experimental research." (PMID 35664436, 2022). "IRF9 and unphosphorylated STAT2 cooperate with NF-kB to induce IL-6 expression, a cytokine that promotes tumour growth of EGFR-driven GBM in an autocrine and paracrine manner." (PMID 36010867, 2022). "Interferon regulatory factor 9 (IRF9) is recruited and expressed upon interferon stimulation and is dependent on cofactors that exert in tumor-suppressing or oncogenic functions via the JAK-STAT pathway." (PMID 33430083, 2021). "The downregulation of IRF9 and VCAN expression was conserved until tumor excision, STAT1, and CDKN1A expression showed decreased tendency and STAT2, and PCNA expression were significantly reduced in the IRF9-knockdown group." (PMID 33430083, 2021). "The analysis indicated a significantly higher expression level of IRF9 and XRCC1 in PsP (diagnosis for pseudoprogression) cases than those for the true tumor progression (TTP) patients in both private and TCGA/TCIA data." (PMID 31795520, 2019). "Conversely, restoring IFN-β expression in OSM-expressing TNBC cells restored the expression of select ISGs (including STAT1, STAT2, IRF9, SOCS1, MX1, and OAS1 and reduced tumor sphere formation and tumor-initiating capacity." (PMID 31036052, 2019). "Consistent with the TCGA UCEC tumor samples, JAK1 and IRF9 were the first and third most significantly downregulated genes, respectively (tab CCLE)." (PMID 29121062, 2017). "The high expression of IRF9 can elicit the antiproliferative activity of IFN- α with the induction of apoptosis in GBM cells, and suppress the tumor progression." (PMID 27421136, 2016). "For example, tumor cell lines with defects in STAT1, IRF9 and Jak1 have been identified and have been found to have reduced in vitro responsiveness to IFN-α." (PMID 20398276, 2010). "Finally, this study shows that by regulating the PI3K/AKT/IRF9 pathway, ITGβ8 promotes the secretion of CCL5 in tumor cells, thereby promoting the M2 polarization of macrophages and tumor progression." (PMID 39535362, 2025). "Gene expression mRNA level analysis exhibited significant upregulation of mRNA levels in tumor tissue: IFNAR1 (3.4-fold increase, p < 0.0001), IRF9 (4.2-fold increase, p < 0.0001), STAT1 (7.1-fold increase, p < 0.0001), and IFI27 (66.3-fold increase, p < 0.0001)." (PMID 39457004, 2024). "Similarly, in vivo results show that the overexpression of IRF9 or STAT2 delays vemurafenib-induced tumor regression, whereas knockdown of IRF9 or STAT2 potentiates tumor growth inhibition." (PMID 36674798, 2023).
tumor (continued). "Using basic IHC, we show that lack of the type I IFN transcription factor IRF9 in tumor cells can predict metastatic relapse." (PMID 31482136, 2019). "We further characterized the functions of IRF9 and XRCC1 in tumor development." (PMID 27421136, 2016). "Knockdown of IRF9, as a central mediator of IFN signalling, would also attenuate any anti-viral crosstalk from Type-II and III IFN produced by the tumour or stroma, which could also possibly mediate this resistance." (PMID 23762429, 2013). "IFI27 is transcribed as a type I interferon (IFN-I) stimulated gene (ISG) mediated by the STAT1/STAT2/IRF9 complex, and activation of the interferon-alpha receptor and increased mRNA levels of ligands and receptors in the TGFB pathway play important roles in the PDAC tumor microenvironment." (PMID 41008826, 2025). "Specifically, CHMP4C, IRF9, and TRAF5 may function as tumor suppressors." (PMID 40893939, 2025). "Thus, IRF9 expression may offer early insight into TNBC patient prognosis and tumor heat, allowing for identification of patients that are unlikely to respond to chemotherapy alone and could benefit from further immune-based therapeutic intervention." (PMID 31482136, 2019).